TERT (telomerase reverse transcriptase)
Diseases named in the same sentence as TERT in open-access papers (continued):
Sharing a sentence is not in itself a finding about the gene and the disease.
cancer (continued). "Notably, marked alterations in mitochondrial function and TERT upregulation are critical characteristics of cancer cells." (PMID 39940762, 2025). "The copy number of TERT may vary in cancerous cells depending on the clinical context, with TERT amplification in ∼2% of cases across a pan-cancer analysis." (PMID 40236328, 2025). "For example, TERT can promote cancer cell growth, invasion, and metastasis in a telomere length-independent manner and is related to treatment resistance, recurrence, and poor outcomes in cancer patients." (PMID 40275278, 2025). "Thus, we developed peptide-gold nanoparticles to induce c-Myc degradation by blocking the interaction between TERT and c-Myc, effectively killing BRAFV600E/pTERT double mutated cancer cells." (PMID 40860184, 2025). "Telomerase reactivation, a hallmark of cancer, not only maintains telomere length via its core components TERT and TERC, but also exerts non-canonical mitochondrial functions—reducing ROS, DNA damage, and apoptosis." (PMID 40492114, 2025). "In particular, the transcription of telomerase reverse transcriptase (TERT), the catalytic subunit of the telomerase enzymatic complex, is tightly regulated in normal cells but is disrupted by multiple possible mechanisms in cancer cells." (PMID 40846797, 2025). "Additionally, combination therapies that involve TERT inhibitors and conventional chemotherapy or radiotherapy are being studied to enhance the overall efficacy of cancer treatments." (PMID 40467649, 2025). "Imetelstat is another compound proposed for future TERT-mutant cancers." (PMID 40332222, 2025). "TERT plays a critical role in the development and progression of various cancers, including HCC." (PMID 40243493, 2025). "Consequently, aberrant expression of the TERT promoter or dysregulation of transcription factors in cancer can result in altered TERT expression, leading to abnormal TA in cells." (PMID 39871386, 2025). "Additionally, the interaction with TERT suggests the potential of F-AuNPs to inhibit telomerase activity, a critical factor in cancer cell proliferation and immortality, which is supported by the observed G0/G1 cell cycle arrest in HepG2 cells." (PMID 40733037, 2025). "TERT can activate several signaling pathways that are pivotal in cancer biology." (PMID 40243493, 2025). "Recent sequencing data indicate frequent PIK3CA H1047R and TERT promoter mutations, with no significant copy number variations, suggesting a distinct molecular pathogenesis compared to other metaplastic carcinomas." (PMID 41301002, 2025). "Additionally, some cancers exhibit amplification of the TERT gene, resulting in increased mRNA and protein levels, as observed in hepatocellular carcinoma and neuroblastoma." (PMID 39126110, 2024). "Other researchers used CRISPR-Cas9 to target the TERT gene in human cancer cells." (PMID 38195537, 2024). "TERT has multiple functions including maintenance of telomere ends, and its activity can have oncogenic effects, such as promoting cell growth and proliferation of cancer cells." (PMID 39495297, 2024). "TERT expression is elevated in cancer but remains low in most tissues." (PMID 39296334, 2024). "This suggests that TERT may contribute to remodeling the extracellular matrix, a critical process that drives cancer stemness, supports cancer cell invasion and requires morphological dynamic changes." (PMID 39078811, 2024). "Additionally, early-phase trials of the TERT-encoding DNA vaccine GRANITE-001 have yielded promising results by stimulating T cell responses against telomerase reverse transcriptase (TERT), an antigen prevalent in various cancers, including HCC." (PMID 39502703, 2024). "In many cancer types, the TERT gene is upregulated, leading to increased telomerase activity." (PMID 38195537, 2024).
cancer (continued). "However, unlike most promoter methylations that are typically associated with gene silencing, TERT promoter hypermethylation has been reported to positively correlate with elevated TERT expression and telomerase activity in various cancers." (PMID 38695555, 2024). "Previous reports indicate that TERT is involved in cancer, inflammation and immune disorders." (PMID 38783329, 2024). "This TERT promoter CpG hypermethylation phenomenon may be attributed as an attempt by cancer cells to sustain only the minimal level of telomerase needed for telomere length maintenance." (PMID 38837897, 2024). "These non-targeted site effects could have compromised the therapeutic effect of targeting TERT, as these mutations could inactivate NFE2L2 and thus promote cancer growth." (PMID 38195537, 2024). "We identified 42 germline variants of interest in 58 of 9089 TCGA participants (0.6%) across all cancer entities, including 8 variants present in the NCI’s TBD cohort (4 loss of function and 4 missense affecting either CTC1, RTEL1, TERT, or WRAP53) (eTable 5 and eTable 15 in Supplement 1)." (PMID 39661387, 2024). "This includes all, e.g., of TERT exon 1, and they remark that this may be a universal correlation and possibly a necessity for TERT expression in cancer cells." (PMID 39000438, 2024). "In this review, we focus on the regulators of TERT and the specific regulatory in cancer." (PMID 38278800, 2024). "In addition, similar to TERT in most cancer types, activation of genes in DNA methylation valleys is associated with DNA hypermethylation." (PMID 38837897, 2024). "Thus, highlighting the moderate growth inhibitory effects of estrogen and progesterone on cancer cell growth in the 76N TERT cells." (PMID 39013992, 2024). "Next, we speculated whether Telo-seq can distinguish between ALT+ and TERT+ cancer cells by plotting the coefficient of variation (CV), a measure of the dispersion in a distribution, against mean telomere length." (PMID 38890299, 2024). "Indeed, all ALT+ cancer cells had a CV above 0.8, whereas the TERT+ cancer cells showed a CV smaller than 0.55, indicating that Telo-seq is an effective method to postulate TMM of cancer cells." (PMID 38890299, 2024). "TERT (Telomerase reverse transcriptase), the catalytic subunit of telomerase, affects telomere length by affecting telomerase activity, and considered to be a useful marker in diagnosis and prognosis of various cancers and a new therapy approach." (PMID 38962012, 2024). "The protein product of TERT is a telomerase reverse transcriptase, which maintains the length of telomere ends by adding the telomere repeat TTAGGG, and its mutation has been detected in approximate 85% of human cancers." (PMID 38184822, 2024). "For example, the TERT gene shows increased activity across almost all the cancers we looked at." (PMID 38495498, 2024). "The authors showed that TERT is a critical factor in the EMT process in cancer progression." (PMID 38278800, 2024). "Interestingly, increasing studies reported that DNA hypermethylation was frequently observed in the promoter region of TERT in human cancers and the promoter methylation was emerged as an epigenetic mechanism of TERT activation." (PMID 38313800, 2024). "TERT is regarded as a key oncogene in the tumorigenesis and development of human cancer." (PMID 38313800, 2024). "Furthermore, cancer-testis antigens (CTAs), minor histocompatibility A (HA)-1, telomerase reverse transcriptase (TERT), and surviving have been recognized as TAAs and are under preclinical investigation." (PMID 39411712, 2024). "This hypothesis is supported by the fact that TERT amplification is relatively rare in cancer and most telomerase-positive cancer cells have short telomeres." (PMID 38837897, 2024).
cancer (continued). "TERT could potentially function as a valuable genomic indicator for detecting and forecasting various types of cancer, while also holding promise as a potential target for therapeutic interventions in the case of OS39." (PMID 38431660, 2024). "The authors showed 73% of 6835 cancers had telomerase reverse transcriptase (TERT) expression and reported that 63% of TERT wild-type tumors in a core set that consisted of 473 T/N pairs expressed TERT, of which 91% showed promoter DNA methylation." (PMID 39000438, 2024). "In BCR-ABL positive cells, Gleevec (imatinib), an inhibitor of receptor tyrosine kinase, induces telomerase translocation out of the nucleolus, indicating that TERT phosphorylation can influence telomerase activity by altering its location in cancer cells, consistent with other findings." (PMID 38278800, 2024). "Furthermore, therapeutic TERT-based vaccines can mediate specific T cell responses in a high proportion of cancer patients." (PMID 36979671, 2023). "Moreover, some dominant oncogenes play a role in a broad range of different cancer types, e.g., common mutations affecting the RAS signaling pathway or the TERT locus." (PMID 37993930, 2023). "We previously identified in cancer cells that TERT AS was regulated by a NOVA1-PTBP1-PTBP2 axis." (PMID 37531400, 2023). "The A255V TERT variant is associated with IPF, BMF, and cancer." (PMID 36833208, 2023). "Human generative cells, cancer cells, and some stem cells have a high TERT activity." (PMID 37283947, 2023). "In addition, a feed-forward transcriptional loop exists between oncogenes and TERT in cancer cells, which is functionally critical for oncogenesis." (PMID 37253773, 2023). "Using two different cell line models of common cancers, we here show that ASEE is suitable to efficiently and super-specifically modify DNA methylation at the TERT promoter region in an allele-specific manner using pathogenic sequence variants or polymorphic single-nucleotide variants as targets." (PMID 37993930, 2023). "Next, we made a serendipitous observation that stem cell density impacted TERT splice variant expression but that cancer cells did not seem to utilize this mechanism." (PMID 37531400, 2023). "Moreover, the regions containing TERT and hTR genes, 5p15.33 and 3q26.3, respectively, are usually amplified in cancer cells." (PMID 36980962, 2023). "Furthermore, unlike conventional promoters, the majority of the CpG islands in the TERT promoter region are hypermethylated in cancer except for a small nonmethylated region upstream of the transcriptional start site (TSS), which coincides with the TPMs." (PMID 37918959, 2023). "Here, we used transcriptomic data from The Cancer Genome Atlas (TCGA) to evaluate the prognostic value of TERT and adaptive immune B and T cells in 11 cancer types, including those with accepted HPV pathogenesis and those with prevalent mutations in the TERT promoter region." (PMID 36909826, 2023). "About 10–20% of total TERT is localized in the mitochondria, both in normal and cancer cells." (PMID 37189709, 2023). "Given the fundamental role of TERT in oncogenesis, it is not surprising that variants within the TERT gene have been associated with increased cancer risk." (PMID 36768147, 2023). "Briefly, we initially evaluated the expression of TERT epitope in our cancer models." (PMID 37996891, 2023). "Known cancer genes such as the telomerase reverse transcriptase (TERT), mixed-lineage leukemia 4 (MLL4), and Cyclin E1 (CCNE1) are preferential integration sites in HCC and about one-third of the genes recurrently targeted by HBV integration are cancer-related genes." (PMID 37927464, 2023).
cancer (continued). "Targeting telomerase, by using direct telomerase inhibitors and immunotherapies, might be effective in all these cancers expressing high levels of TERT gene." (PMID 38033865, 2023). "GX301 and Vx-001 are also the TERT peptide vaccines in clinical trials for treating cancer." (PMID 38111043, 2023). "In addition, new compounds that selectively stabilize the G-quadruplex in mutant TERT promoters and inhibit telomerase expression have been evaluated in preclinical studies for their inhibitory effect on telomerase and killing of cancer cells." (PMID 38033865, 2023). "The mechanisms to maintain telomere length by telomerase in cancer cells include mutation of the TERT promoter, abnormal amplification of the TERT and TERC genes, rearrangements of the TERT gene, and genetic variants of the TERT gene and its promoter." (PMID 36910209, 2023). "TERT is the direct target gene of c‐Myc and regulates the stability of c‐Myc in cancer." (PMID 37983928, 2023). "TERT expression/telomerase activity can be detected in up to 90% of primary human cancers." (PMID 37226235, 2023). "Increased TERT expression restores telomerase activity, suggesting that transcriptional control may play a role in a wide array of diseases, including cancer and aging." (PMID 38264209, 2023). "Given that AAD and TERT promoter mutations are both independent prognostic factors for cancer-specific mortality, and the likelihood of high prevalence of TERT promoter mutation in older AAD, our study group sought the correlation of AAD and TERT promoter mutation in cancer-specific mortality." (PMID 37948420, 2023). "Stable cfDNA levels, normal ERBB2 copy number, and the absence of TERT C228T mutations indicate a stable cancer status." (PMID 37945655, 2023). "Thus, an interesting approach is to use immune cells, such as T cells targeting TERT+ cancer cells by the recognition of TERT antigens bound to MHC." (PMID 37189709, 2023). "Consistent with this crucial role in pathogenesis, circulating cell-free TERT mRNA may be detected in the plasma of cancer patients." (PMID 36980987, 2023). "Hence, our study adds to the role of TERT expression in cancer metastasis and potentially also immune resistance." (PMID 37418389, 2023). "The synergistic effect of TERT and CDH16 on cellular adhesion and cancer progression may explain the worse DFS when TERT mutation and CDH16 loss coexist." (PMID 37899424, 2023). "Our work describes new regulators of TERT gene expression with possible roles in cancer." (PMID 37918959, 2023). "Nevertheless, these results support A-549 to be a promising cancer model for TERT silencing." (PMID 37993930, 2023). "Re-expression of TERT can lead to immortalization of cancer cells and enhanced survival." (PMID 37620318, 2023). "Minus beta TERT, despite there being a frame shift and a premature termination codon in frame in exon 10, has also been reported to form a protein and to have dominant-negative effects in certain cancer cells." (PMID 37531400, 2023). "Genetic variants near TERT, TERC, or OBFC1 may have independent impact on the risk of certain types of cancer, which violates the exclusion restriction assumption of MR." (PMID 37232505, 2023). "Indeed, the majority (85%–90%) of cancers maintain their telomeres by reactivating TERT expression, which contributes to their indefinite proliferative potential." (PMID 37918959, 2023). "In one example, a transgenic mouse carrying the entire 50 kb human TERT locus was used to show that in vivo expression of human and mouse TERT genes differ significantly, raising awareness about the use of mouse models for human cancer and aging." (PMID 38147065, 2023). "In addition, iHerd highlighted GABPA, a TF selectively recruited to the mutant form of the TERT promoter to activate TERT’s transcription in most human cancers." (PMID 37695793, 2023).
cancer (continued). "In a previous study, BRAF and RET/PTC1 rearrangement and TERT promoter mutations were associated with more aggressive cancers than malignancies without one of these mutations." (PMID 37370711, 2023). "TERT has been reported to function as an oncogene in various types of cancer." (PMID 37575241, 2023). "For instance, the up-regulation of ZNF148 following knockdown of all other factors, including E4F1, could be a compensatory mechanism to up-regulate TERT expression, which is vital for unlimited cancer cell proliferation." (PMID 37918959, 2023). "Furthermore, hypermethylation of the TERT promoter region has been demonstrated to be one factor behind the dysregulation of TERT function in cancer cells." (PMID 36831683, 2023). "Using nanoparticles to deliver TERT siRNAs into cells can enhance the cancer suppression efficacy." (PMID 38111043, 2023). "Usually, TERT is highly expressed in stem cells and cancer cells." (PMID 38054695, 2023). "However, a potential drawback of the ectopic expression of TERT is the development of immortal proliferative properties (i.e., cancer), because lengthening telomeres allows cells to bypass senescence." (PMID 37707950, 2023). "Therefore, identifying differences in TERT regulation between stem cells and cancer cells is essential for developing telomerase inhibition-based cancer therapies that reduce damage to stem cells." (PMID 37531400, 2023). "They hypothesized that short telomeres uncontrolled by TZAP were important for cancer progression, and that TZAP expression was linked to TERT expression." (PMID 36556980, 2022). "In addition, accumulating evidence supports that TERT/telomerase exhibits oncogenic activities far beyond its telomere-lengthening action, thereby contributing to multiple hallmarks of cancer." (PMID 35326537, 2022). "The TERT promoter is commonly genetically altered and/or methylated in cancer." (PMID 36011010, 2022). "It is known that TERT is a component of telomerase, a reverse transcriptase ribonucleoprotein complex that maintains telomere length in cells with high proliferative ability, and that it plays a key role in cancer formation." (PMID 36557983, 2022). "There is an abundance of recent literature on the role of epigenetic modifications altering the expression of TERT in cancer via transcriptional and post-transcriptional mechanisms, but the potential for the epigenetic states promoting its mutagenesis has been hypothetical." (PMID 35739588, 2022). "TERT -146 C>T activates telomerase and enables cancer cells to achieve unlimited proliferation." (PMID 35053139, 2022). "TERT (telomerase reverse transcriptase) is a rate-limiting catalytic subunit of telomerase that is required for telomere length maintenance and plays a key role in stem cells, aging and cancer." (PMID 36624801, 2022). "Targeting of TERT/telomerase is currently attempted for cancer therapy." (PMID 35326537, 2022). "Indeed, many endogenous and exogenous oncogenic factors are identified to activate the TERT transcription and these findings have greatly contributed to understanding of cancer-specific TERT regulation." (PMID 36713366, 2022). "Multiple oncogenic roles of TERT in cancer development and progression have been established." (PMID 35159976, 2022). "Telomerase reverse transcriptase, which is encoded by the TERT gene, forms an important component of the telomerase complex and TERT mediated de novo telomeric DNA synthesis in rapidly proliferating cancer cells prevents chromosomal ends from being recognized as sites of DNA damage." (PMID 34549366, 2022). "Thus, the UTSS hypermethylation is cancer-specific and likely an epigenetic mechanism to induce TERT expression by unlashing repressors from the promoter." (PMID 36713366, 2022). "We conducted meta-analyses to assess relationships of 23 variants in TERT-CLPTM1L region with 12 cancers and 1 non-cancer disease under an additive genetic model." (PMID 35847915, 2022).